RNU6-619P (RNA, U6 small nuclear 619, pseudogene)
Gene: Small nuclear RNA gene on chromosome 2 (222,498,291 to 222,498,398, forward strand). Ensembl gene ENSG00000202016.
Homologues: Orthologues: chimpanzee U6 (100% identical), macaque U6 (87% identical), guinea pig U6 (81% identical), dog U6 (80% identical), dog U6 (78% identical), dog U6 (70% identical). Paralogues in human: RNU6-1060P (87% identical), RNU6-116P (86% identical), RNU6-132P (86% identical), RNU6-15P (86% identical), RNU6-166P (86% identical), RNU6-199P (86% identical), RNU6-22P (86% identical), RNU6-41P (86% identical), RNU6-517P (86% identical), RNU6-1303P (85% identical), RNU6-17P (85% identical), RNU6-18P (85% identical), and 1282 more.